IFNG (interferon gamma)
Diseases named in the same sentence as IFNG in open-access papers (continued):
Sharing a sentence is not in itself a finding about the gene and the disease.
Premature ovarian insufficiency (1 paper, 2021). Amenorrhea due to loss of ovarian function before the age of 40. "An imbalance between pro-inflammatory cytokines such as IFNγ and TNFα and anti-inflammatory cytokines such as IL-10 has also been reported to play a critical role in the pathological mechanism of premature ovarian insufficiency." (PMID 34868029, 2021).
primary effusion lymphoma (1 paper, 2009). A large B-cell lymphoma located in the body cavities, characterized by pleural, peritoneal, and pericardial fluid lymphomatous effusions and that is always associated with human herpes virus-8 (HHV-8). "In vitro studies showed that inflammatory cytokines, such as interferon gamma, induce HHV-8 replication in the PMBCs of HIV-infected patients and in primary effusion lymphoma cell lines." (PMID 19946591, 2009).
pterygium (1 paper, 2022). A wedge-shaped fibrovascular lesion arising from the bulbar conjunctiva and extending to the cornea. "Interferon-gamma response belongs to immune responses which have been associated with pterygium." (PMID 36187094, 2022).
reactive disorders (1 paper, 2025). "Cutaneous manifestations in adult-onset immunodeficiency (AOID) resulting from anti-interferon-gamma autoantibody (AIGA) are prevalent and can be classified into infective and reactive disorders." (PMID 40918099, 2025).
retinal diseases (1 paper, 2022). "The roles of angiogenic and proinflammatory factors, including VEGF, TNF, TGFB1, CASP3, IL6, IFNG, and IL1B, and their association with miRNAs and the specified proteins in retinal diseases have been previously reported." (PMID 36180575, 2022).
Rett syndrome (1 paper, 2024). A severe neurodevelopmental disorder affecting the central nervous system.
serous ovarian adenocarcinoma (1 paper, 2020). "In contrast, when PBMCs were incubated with a variety of high grade serous ovarian adenocarcinoma cell lines, including OVCAR8, OVCAR3, and OVCAR5, robust NK cell degranulation and intracellular IFNγ production was seen compared to no treatment and rhIL-15 alone." (PMID 32961861, 2020).
undifferentiated pleomorphic sarcoma (1 paper, 2019). An undifferentiated soft tissue sarcoma characterized by the presence of a pleomorphic malignant cellular infiltrate. "Neutrophil infiltration was found to be associated with better prognosis and higher IFNG expression in human undifferentiated pleomorphic sarcomas (UPS) and in selected tumors." (PMID 31257026, 2019).
uterine infection (1 paper, 2022). "The top three upstream regulators predicted to be activated in the endometrium of pregnant cows after uterine infection include 1) IFNG (cytokine); 2) IFNA2 (cytokine); and 3) PRL (cytokine)." (PMID 35358206, 2022).
vulvar lichen sclerosus (1 paper, 2017). A chronic inflammatory disorder of unknown etiology that affects the vulva.
tumor (13,578 papers, 1985 to 2026). "The anti-tumor effects of M1/42 depend on NK cells and are associated with upregulation of genes involved in antigen processing, interferon gamma responsiveness, and Th1 cytokine production, while downregulating inhibitory PD1/11 signaling." (PMID 42182210, 2026). "This inhibition rate was significantly higher than that of the rHER2 ECD-IFNγ mRNA-LNP variant, which achieved 21.9% tumor inhibition and induced anti-IFNγ neutralizing antibodies." (PMID 41993212, 2026). "Overall, our data demonstrate that a CD8/monocyte crosstalk is potentiated in tumours insensitive to IFNγ and underlies their control." (PMID 39746898, 2025). "The concept works by releasing LNPs from the microparticle complex to deliver IFNγ mRNA to tumor-associated macrophages (TAMs) following intratumoral injection." (PMID 40557148, 2025). "Additional expression of therapeutic genes encoding e.g., IFNγ enables local activation of prodrugs or enhancement of the immune response within the tumor." (PMID 41294877, 2025). "These pathomechanistic pathways cause a reduced NK-cell and T-cell cytotoxicity, as well as an IFNγ production in the tumor microenvironment, causing a facilitated immune escape." (PMID 41228220, 2025). "Tumor-associated neutrophils polarize into N1 (anti-tumor) or N2 (pro-tumor) phenotypes; N1 reprogramming via interferon gamma (IFN-γ) conditioning has shown therapeutic promise." (PMID 41181123, 2025). "Conversely, tumours with robust T cell-inflamed gene expression signatures that include IFNG and its downstream chemokines are associated with improved overall survival." (PMID 41366257, 2025). "In mouse models, both IFNγ and TNFα were found to be required for the killing of antigen‐loss variant tumor cells in established tumors." (PMID 40178291, 2025). "We also found changes in mdTAM_4 in anti-PD-L1-treated tumours, with several inflammatory pathways preferentially enriched, particularly ‘Hallmark Interferon gamma response’." (PMID 40523200, 2025). "The role of iNKT cells is linked to an increased anti-tumor immune response through production of IFNγ or IL-12." (PMID 40102596, 2025). "Mechanistically, mutations in the PPP2R1A gene induce a strong interferon gamma response in tumor cells, which enhances infiltration of activated CD8+ T cells into the tumor." (PMID 40737443, 2025). "These cells were also clearly distinct from the tumor-associated CD69+IFNG+PRF1– and the dysfunctional/low cytotoxic NR4A1+ CD158a (KIR2DL1)+ CD158e (KIR3DL1)+ NK cell populations described in the other studies." (PMID 40530504, 2025). "The R-GEM/VNP system loaded with attenuated Salmonella mediates sustained anti-tumor effects, while a variant carrying IFNγ-secreting bacteria effectively reverses the immunosuppressive microenvironment in multiple metastatic lung cancer models." (PMID 41459510, 2025). "SFV encoding TNFα and IFNγ are expected to inhibit the pro-tumorigenic effect of cancer cells and enhance macrophage anti-tumour gene expression, promoting an M1-like phenotype." (PMID 40547518, 2025). "Tumor-intrinsic-resistant mechanisms involve low tumor mutational burden, compromised antigen presentation machinery, alterations in the interferon-gamma pathway, and loss of tumor suppressors such as STK11/LKB1." (PMID 40718320, 2025). "Interferon gamma is a pivotal cytokine that coordinates tumor-associated immune response, showing the potential of interferon gamma response genes as the risk predictor in LUAD." (PMID 40860289, 2025). "GSEA hallmark analysis also revealed that hallmarks of interferon-gamma response and IL6_JAK_STAT3 pathway were downregulated in old tumor cells." (PMID 41332581, 2025). "On the one hand, TNFR2 has been associated with an increased production of interferon gamma (IFN-γ) by NK cells, but on the other hand, it has also been linked with loss of NK cell cytotoxic capacity promoted by the tumor microenvironment." (PMID 40612956, 2025).
tumor (continued). "M1 tumor-associated macrophages (M1 TAMs) are typically activated by Toll like receptors (TLRs), which consist mainly of bacterial lipopolysaccharide (LPS), interferon-gamma (IFN-γ), and HSPs." (PMID 40688079, 2025). "Overall, analysis of human datasets corresponds to our murine model and shows that CD8-monocyte signatures can be found in tumours with mutations in the IFNγ-pathway." (PMID 39746898, 2025). "Immune cell infiltration analysis identified a significant presence of CD8+‐T cells, IFNγ‐6/‐18 in the low‐risk group, suggesting an immunologically favorable tumor microenvironment." (PMID 39840456, 2025). "These ferroptosis carriers are also affected by the production of interferon γ (IFNγ) which leads to ferroptosis, linked to lipid peroxidation in tumor cells." (PMID 40136510, 2025). "These mutations render tumor cells less responsive to the antiproliferative effects of T cell–derived IFNγ, allowing cancer cells to escape immune attack." (PMID 41019045, 2025). "Interferon-gamma (IFN-γ) plays a crucial role in the polarization of tumor-associated macrophages (TAMs) towards an M1-like phenotype in the TIME." (PMID 40141426, 2025). "Although the overall number of ILC1s increases, their ability to produce IFNγ is diminished, reflecting a loss of their anti‐tumour capabilities and enabling tumours to evade immune destruction." (PMID 40899118, 2025). "An evaluation of T cell function in LKB1-deficient tumours revealed significantly less IFNg and Ki-67 expression in CD4+ and CD8+ tumour-infiltrating T cells." (PMID 40647497, 2025). "Overall, our study demonstrates that tumour-derived mutations in the IFNγ pathway can trigger a remodelling of the immune landscape underlying the control of those mutated clones." (PMID 39746898, 2025). "We found that loss of IFNγR1 on tumour cells results in intra-tumoural IFNγ accumulation, which induces pro-inflammatory signalling of immune-infiltrating populations." (PMID 39746898, 2025). "In support, PD1-deficient ILC1 display enhanced IFNγ and granzyme B expression, delaying tumor growth." (PMID 41177809, 2025). "This enhancement was linked to an increase in intratumoral mature DCs as well as IFNγ+ CD8 tumour‐infiltrating lymphocytes." (PMID 39801378, 2025). "This systemic reaction is associated with the release of interferon-gamma (IFN-γ) from activated T cells or tumor cells." (PMID 41393569, 2025). "CALR is expressed in nearly all cells in the TME, IL1R1 is mainly expressed in tumor-associated fibroblasts and endothelial cells, and the expression levels of IFNG and IFNB1 are minimal, primarily by T lymphocytes." (PMID 40928500, 2025). "Baseline CD8+ and CD3+ tumor-infiltrating T cell density, IFNγ pathway and effector T cell gene expression, tumor mutational burden and pre-surgery circulating tumor DNA correlated with pathological response across treatments." (PMID 40993242, 2025). "Deep infiltration of tumor-associated macrophages and Ly6G+ myeloid suppressor cells in distal tumors was significantly reduced after treatment with Nano-IFNγ/Zole." (PMID 39776793, 2025). "Specifically, OMVs have been shown to drive a shift in the TME toward a pro-TH1 immune profile, characterized by the upregulation of key cytokines, such as CXCL10 and interferon-gamma (IFN-γ), which are associated with enhanced anti-tumor immunity." (PMID 40927726, 2025). "In our study, we found that the environment of GBM cells exposed to MSCMel presented reduced levels of IFNγ, TNFα and IL-1β, and this condition was associated with a less aggressive tumor phenotype." (PMID 40083939, 2025). "Many clinical reports have associated acquired resistance to ICB with loss of IFNγ response by tumour cells via signalling pathway mutations." (PMID 39746898, 2025). "It is therefore important to understand the factors that contribute to eliciting a potent anti-tumour response during tumour escape and how it integrates with mutations in the IFNγ pathway." (PMID 39746898, 2025).
tumor (continued). "CD8 + T cell-induced interferon gamma (IFN-γ) signaling with tumor cells is also positively associated with response." (PMID 41185627, 2025). "Tumor-associated PD-L1 is primarily induced by tumor-infiltrating lymphocyte (TIL)-derived interferon gamma (IFN-γ), which promotes apoptosis and dysfunction of activated T-cells, thereby attenuating the immune response and facilitating tumor growth." (PMID 40486875, 2025). "Together, IFNγ and IL-12(p70) promote nitric oxide synthase expression in macrophages, a hallmark of M1 anti-tumor polarization, and suppress TGFβ signaling by downregulating its receptor TGFβRII." (PMID 41155334, 2025). "In total, this supported our initial findings seen in the Xena and TARGET tumor samples but also provided key insight into which areas of the IFNγ signaling pathway can change upon ARID1A loss." (PMID 40082458, 2025). "These cells express elevated levels of PD-1, which, in the tumor setting, has been linked to the loss of Treg cell suppressive functions, and similar to our observation, increased secretion of IFNγ." (PMID 40164596, 2025). "There had been a noteworthy positive correlation seen in the TUM district (tumor tissue) between the concentrations of IL-18 and traditional Th1-associated cytokines, such as IFNγ, TNF-α, and IL-12." (PMID 41179937, 2025). "At baseline, mdTAM_4 was particularly high in Ifngr1 expression, despite low expression of genes associated with IFNγ stimulation, potentially indicating an unutilised capacity to respond to type-II interferon that is held in check by the tumour environment." (PMID 40523200, 2025). "Using single-sample GSEA, multiple tumour types scored higher for CD8-monocyte enrichment in IFNγ-pathway mutation-containing datasets compared to controls." (PMID 39746898, 2025). "In contrast to Detox-iCAF, IL-iCAF are primarily associated with normal breast epithelial structures and found in the intralobular stroma enriched in Adipo-EC, while IFNγ-iCAF are associated with lymphocyte aggregates and enriched in the tumor bed." (PMID 38561380, 2024). "Although various studies report low levels of IFNγ in BCC, elevated IFNγ in the tumor infiltrate has been associated with tumor regression." (PMID 39407789, 2024). "Genetic alterations within the tumor cells, such as mutations in the interferon - gamma pathway genes, can also lead to primary resistance." (PMID 39720720, 2024). "In sharp contrast, MH-induced curtailment of tumor growth was completely abrogated in IFNγ-deficient mice, demonstrating mechanistically that MH most likely exerts its immunomodulatory effect via the activation of the IFNγ pathway." (PMID 38444857, 2024). "Cluster 1 exhibited enrichment for the coagulation, complement, interferon-gamma response, bile acid metabolism, and other pathways associated with tumor matrix activation and inflammatory activity." (PMID 39530087, 2024). "CXCL9 and CXCL10 mediated accumulation of CD8+ T cells in tumors occurs following checkpoint blockade and these IFNγ-dependent events are mediated by tumor-associated macrophages." (PMID 38786066, 2024). "Some soluble cytokine encoded by the IFNG gene are involved in tumor clearance, dormancy, escape, and progression." (PMID 39138733, 2024). "In murine MB49 cells, loss of FOXP3 led to smaller tumors, decreased expression of PD-L1, and increased CD8+ T cells in tumor tissues in vivo but preserved tissue expression of IFNγ, supporting loss of IFNγ responsiveness." (PMID 39099201, 2024). "In OC lesions, Tregs suppress the immune response to tumor-associated antigens by inhibiting the secretion of interferon-gamma (IFN-γ), interleukin-2 (IL-2), IL-10, and TGF-β by effector T cells." (PMID 39200270, 2024). "HLA-E expression in tumor cells can be regulated in response to immune associated factors such as IFNγ, TNFα, IL-1β and IL-27, which are also associated to GMM educated immune cells." (PMID 39229258, 2024).
tumor (continued). "Tumor regulatory T cells (Tregs) promote M2-like tumor-associated macrophages by suppressing IFNγ production by CD8+ T cells, which blocks SREBP1-dependent fatty acid metabolism in macrophages." (PMID 39402302, 2024). "In a murine PDAC model, we found that intrinsic loss of SIN3B within tumor cells enhances CD8+ T cell infiltration by increasing the secretion of IFNγ‐induced chemokines CXCL9 and CXCL10." (PMID 39316363, 2024). "CD137+ T cells present at the tumor site have been found to be associated with the strength of the anti-tumor immune response mainly expressed by tumor-infiltrating lymphocytes that release IFNγ." (PMID 38254759, 2024). "Meanwhile, decreased suppressive cytokine IL10 and increased tumor-killing cytokine IFNγ expression were detected in IFITM3-deficient TI-Treg cells." (PMID 38167862, 2024). "JAK1 and JAK2 genes encode signal transducers that respond to IFNγ by increasing antigen presentation, producing chemokines to attract T-cells, and triggering tumour cell apoptosis." (PMID 38552610, 2024). "IFNγ has been strongly associated with anti-tumor efficacy in preclinical and clinical studies;21 however, the role of TNFα in promoting tumor immunity is more ambiguous and most likely context dependent." (PMID 38333710, 2024). "In a preclinical study, HER2 BAT-associated activated T cells demonstrate anti-tumor cytotoxicity, effective intratumoral trafficking, and secretion of cytokines such as IFNγ, TNFα, and GM-CSF, upon tumor engagement." (PMID 38801069, 2024). "Underexpressed IFNG was also associated with more advanced disease (p = 0.02) and the presence of isolated tumor cells within the lymph nodes (N0 I+, p = 0.04)." (PMID 38831317, 2024). "The mechanisms underlying tumor intrinsic mechanisms of resistance to checkpoint blockade include genetic and epigenetic alterations, disruption in IFNγ signaling, upregulation of PD-L1 expression, and the influence of immunosuppressive cytokines." (PMID 38903504, 2024). "PD-L1 and MHC-I inducibility by IFNγ in vitro is associated with tumor outgrowth of MOC1 clones in vivo." (PMID 39009951, 2024). "To this end, we have developed a CRISPR/Cas9 approach to generate murine tumor models refractory to PD-1/-L1 inhibition due to APM/IFNγ signaling mutations." (PMID 38427670, 2024). "These neoantigen-augmented iPSC cancer vaccines remarkably enhanced neoantigen-reactive CD8+ T cell responses and promoted the production of antitumor cytokines such as IFNγ and GzmB to eradicate tumor cells and decrease the risk of distant metastasis." (PMID 38821980, 2024). "Increased levels of IRF1 in tumor cells in this study were associated with increased secretion of IFNγ by infiltrating NK and NKT cells and with induction of apoptosis by the CXCL10/CXCR3 paracrine axis." (PMID 38396830, 2024). "Mouse splenocytes were utilized to assess for a systemic anti-tumor immune response using an IFNγ enzyme-linked immunospot (ELISPOT) assay." (PMID 39276533, 2024). "Inversely, mutations in the IFNγ pathway can increase tumor cell sensitivity to ICIs by enhancing the secretion of chemokines that recruit effector T and NK cells to the tumor tissue." (PMID 38903504, 2024). "In short, the light-induced local release and persistence of IFNG caused remarkable alterations in the tumor microenvironment and triggered tumor regression, primarily by upregulating the expression of immune-related genes and recruiting effect immune cells." (PMID 39080467, 2024). "In contrast, immune-inflamed tumors are characterized by a TME rich in interferon-gamma (IFN-γ), a high tumor mutational burden, a large population of TILs, and an elevated expression of major histocompatibility complex (MHC) class I/II in tumor cells." (PMID 39066359, 2024). "It has been observed by another research team that low HIF-1α expression is associated with elevated IFNG expression in tumor-infiltrating NK cells in humans." (PMID 38808131, 2024).